S100B (S100 calcium binding protein B)
Diseases named in the same sentence as S100B in open-access papers (continued):
Sharing a sentence is not in itself a finding about the gene and the disease.
depression (continued). "More studies are needed to verify the dynamics of S100B serum changes among patients with depression." (PMID 35448545, 2022). "We also aimed to investigate the differences in BDNF, proBDNF, and S100B levels between depression in the course of bipolar disorder (BD) and major depressive disorder (MDD)." (PMID 35448545, 2022). "Thus, a possible imbalance of pro-inflammatory cytokines associated with VEGF imbalance and the presence of peripherally circulating s100β may evidence this shared signaling pathway linked to depression, symptom severity, response to antidepressant treatment, and suicide." (PMID 36559251, 2022). "Self-rated depression severity was significantly positively correlated with levels of S100B when all three groups were combined (rs = 0.319, P < 0.001)." (PMID 35585111, 2022). "Compared to the studies on S100B levels in depression, the research on S100B as a biomarker in anxiety, especially in GAD, is limited." (PMID 35815053, 2022). "Previous studies in adults show elevated S100B serum levels in patients with mood disorders (both depression and mania) compared to the control group." (PMID 34099858, 2021). "S100B levels in the group of patients with unipolar depression correlated positively with WBC count (r = 0.323, p = 0.001), total protein (r = 0.359, p < 0.001), and AQs (r = 0.327, p = 0.001)." (PMID 34021122, 2021). "In the rat depression model, chronic unpredictable mild stress significantly increases S100B expression (on mRNA and protein level) in the hippocampus." (PMID 34099858, 2021). "In humans, peripheral levels of S100B have shown to be elevated in MDD patients and associated with depression severity." (PMID 34354565, 2021). "Our results are in contrast with studies where S100B was significantly elevated in female patients with major depression compared to controls." (PMID 34099858, 2021). "In our study, we examined the relationship between plasma levels of mBDNF and S100B and depression severity, obtained during a randomized, placebo-controlled trial of ketamine in Selective Serotonin Reuptake Inhibitor (SSRI)-resistant MDD." (PMID 34354565, 2021). "Although elevated levels of S100B in MDD patients and positive correlations between S100B levels and depression severity have been reported, also reduced levels have been found in cerebrospinal fluid of depressed subjects." (PMID 34354565, 2021). "Changes in S100B levels were also found in patients with psychiatric diseases, such as schizophrenia, depression, and bipolar disorder, but more studies are needed to establish S100B as a reliable clinical biomarker." (PMID 32722137, 2020). "Does baseline S100B differentially predict changes in overall depression severity with escitalopram monotherapy versus antidepressant combinations?" (PMID 31861074, 2019). "Several reports have found elevated levels of S100B in peripheral circulation of patients with depression." (PMID 31861074, 2019). "S100B is already correlated to depression through two mechanisms, as described in the current literature." (PMID 30581620, 2018). "In conclusion, EGb was an effective adjunctive treatment in improving depressive symptoms and reducing the expression of S100B in serum in the treatment of elderly patients with depression." (PMID 30278520, 2018). "Several studies emphasize the importance of S100B for major depressive disorders: in males with minor depressive episodes, S100B levels are increased when compared to healthy subjects." (PMID 29545905, 2018). "Our study supports this result, as the baseline S100B levels were significantly higher in remitters and correlated negatively with baseline depression severity." (PMID 29545905, 2018). "Accordingly, the present study was carried out to explore the efficacy and adverse effects of EGb as an adjunctive treatment of elderly patients with depression and the effect on the expression of serum S100B." (PMID 30278520, 2018).
depression (continued). "In S100B and Tumor Necrosis Factor-a (TNF-a), a protein linked to depression through inflammation, serum levels were measured." (PMID 30581620, 2018). "Intriguingly, S100B at baseline has been considered as a possible marker for cognition side effects and depression." (PMID 29545905, 2018). "No published study has examined the effect of the antidepressant drug venlafaxine on S100B in animal models of depression." (PMID 27931233, 2016). "The most recent meta-analysis including a very high number of subjects has shown that fluctuations in serum levels of S100B seem to be state markers for major depression." (PMID 27931233, 2016). "After treatment with venlafaxine, the increased expression of S100B mRNA and protein levels was decreased and the release of proinflammatory cytokine declined in the hippocampus, leading to improvements in the depression-like behaviors." (PMID 27931233, 2016). "A previous study revealed that significant level of stress, depression, and anxiety is accompanied by increased blood-brain barrier permeability and increased serum S100B level." (PMID 27073715, 2016). "Venlafaxine treatment (10 mg) improved these chronic stress induced depression-like behaviors and decreased the elevated S100B levels to the normal range." (PMID 27931233, 2016). "These contradictory findings indicate that the role of S100B in major depression is rather complex and still far from being understood." (PMID 26364276, 2015). "S100B levels were also found to be higher in serum samples of patients with schizophrenia, major depression, and bipolar disorder." (PMID 26364276, 2015). "To control whether elevated S100B levels are associated with more severe depression and therefore are more likely to be associated with an increased treatment response, we calculated the correlation between baseline S100B levels and severity of depression at baseline as assessed by HAM-D scores." (PMID 26364276, 2015). "The statistical power calculations using G-Power for Mann-Whitney tests were based on the previous meta-analyses of BDNF and S100B alterations in major depression." (PMID 26500502, 2015). "S100B levels and Hamilton Depression Rating Scale (HAM-D) scores were assessed at baseline, after 7 weeks of treatment, and after 6 months." (PMID 26364276, 2015). "In particular the glial protein S100B, a neuro- and gliotrophin inducing plasticity, seems to be involved in the pathogenesis and treatment of psychiatric diseases such as major depression and schizophrenia." (PMID 22916238, 2012). "Same serum S100B elevation was observed in patients with major depression, with decrease in serum S100B levels during clinical improvement after antidepressant treatment." (PMID 21350721, 2011). "The gila-derived neurotrophic marker S100B, a calcium-binding protein produced mainly by astrocytes, has been shown to be increased in the serum of patients with a melanchlolic subtype of major depression." (PMID 21614209, 2010). "Studies consistently show that S100B is elevated in mood disorders; more strongly in major depressive than bipolar disorder." (PMID 20585358, 2010). "Serum concentrations of the glial marker protein S100B are elevated in patients with mood disorder, major depression and mania, when compared with healthy control subjects." (PMID 20585358, 2010). "Our study has demonstrated that stress and depression decrease S100B and RAGE/SRAGE expression and antidepressant treatment reverses or blocks these effects." (PMID 21614209, 2010). "S100B levels are increased in CSF and serum of patients with depression, and the best response to therapy is predicted by the highest levels of S100B." (PMID 20827311, 2010). "Accumulating data from clinical studies convincingly demonstrate increased S100B levels in the serum of patients suffering from acute or chronic schizophrenia as well as depression." (PMID 19936105, 2009).
depression (continued). "Despite these limitations, this study is the largest serum S100B study performed in depressive patients to date and provides useful information regarding the relationship between serum S100B levels and depression." (PMID 20046365, 2008). "The serum S100B levels and clinical assessments, which included Hamilton depression rating scores, were measured at baseline and after 6 weeks of treatment with antidepressants." (PMID 20046365, 2008). "Additionally, elevated levels of S100β, NSE, and PLT are identified as risk factors for the development of depression." (PMID 40589656, 2025). "Collectively, S100B may serve as a valuable biological indicator with clinical significance for the diagnosis and treatment of depression." (PMID 39451987, 2024). "While there are no reported genetic polymorphisms of S100B in depression, this molecule has been linked to the development of depressive symptoms in subjects with comorbid somatic illnesses, such as end-stage renal diseases and myocardial infarction." (PMID 39451987, 2024). "However, the compensatory–restorative mechanism and neuroimmune functioning differ in patients with depression; therefore, some researchers report elevated S100B levels in patients with Affective Disorders." (PMID 37763190, 2023). "In a cross-sectional naturalistic study, the S100B, MBP and GFAP levels in the blood serum were compared between two diagnostic groups (patients with Depressive Episode (DE, n = 28) and patients with Recurrent Depressive Disorder (RDD, n = 21)), and healthy controls (n = 25)." (PMID 37763190, 2023). "Therefore, the aim of the current study was to examine GFAP and S100B levels in the CSF of patients with major depression to better understand their role in affective disorders." (PMID 34021122, 2021). "Second, as an immune-modulator, S100B concentrations may be affected by immune function, which is known to be dysregulated in depression." (PMID 34354565, 2021). "Extensive studies on S100B in depression have been conducted in the last two decades." (PMID 34021122, 2021). "Elevated serum concentrations of S100B have been found in patients with depression and may prove valuable for evaluating both diagnosis and treatment response." (PMID 34021122, 2021). "Multiple lines of investigation suggest the utility of measuring levels of S100B in depression." (PMID 31861074, 2019). "In some studies S100B are reported higher in depression when studied in general population." (PMID 30581620, 2018). "Given the small number of studies addressing S100B and depression it is possible that there are more unknown pathophysiological pathways that influence S100B kinetics." (PMID 30581620, 2018). "We speculate that venlafaxine may ameliorate the depression-like behaviors by influencing the expression of S100B in the hippocampus." (PMID 27931233, 2016). "Accumulating evidence has indicated that S100B may be involved in the pathophysiology of depression." (PMID 27931233, 2016). "We speculate that venlafaxine may ameliorate the depression-like behaviors by influencing the expression of S100B in the hippocampus, which may work through its anti-inflammatory effect." (PMID 27931233, 2016). "In summary, we found that chronic stress led to depression-like behaviors and increased S100B expression and mRNA levels in the hippocampus, suggesting that increased S100B may be relevant to the pathology of depression." (PMID 27931233, 2016). "Our findings showed that venlafaxine treatment (10 mg) may improve the depression-like behaviors and decrease over-expression of S100B protein and mRNA in the hippocampus in a rat model of depression." (PMID 27931233, 2016). "Moreover, the fact that differences in S100B are less prominent than in major depression suggests that clinical presentation mirrors to some extend molecular changes." (PMID 26500502, 2015). "S100B, as an index for glial alterations, is modified by age in major depression." (PMID 26500502, 2015).
depression (continued). "Increased S100B in minor depression may indicate early glial pathology that precedes specific neuronal changes such as in major depression." (PMID 26500502, 2015). "While there are some inconsistent reports whether S100B levels decline with treatment response or not, the present study strongly suggests that S100B rather is a trait marker for antidepressant responsiveness than a state marker for depression severity." (PMID 26364276, 2015). "Lower levels below 300 ng/l have been detected in neuropsychiatric disorders, such as depression or schizophrenia and might describe a regenerative action through S100B, and due to their low concentration less likely a neurodegenerative process." (PMID 22916238, 2012). "Recently, it has been suggested that S100B may play a crucial role in the pathogenesis and treatment of frequent psychiatric disorders such as major depression and schizophrenia." (PMID 22916238, 2012). "Accordingly, it remains to be clarified whether elevated serum S100B could indicate an impairment in the blood-brain barrier, as has been described for depression." (PMID 20585358, 2010). "Serum S100B is higher in major depressive disorder than bipolar disorder." (PMID 20585358, 2010). "We purpose that S100B/RAGE (sRAGE) interactions might participate in the pathobiology of depression and could be a target for the action of antidepressant drugs." (PMID 21614209, 2010). "Successful antidepressive treatment reduces S100B in major depression." (PMID 20585358, 2010). "Most studies based the “astrocytic hypothesis” of schizophrenia and depression on increased serum or CSF levels of the astrocytic S100B protein." (PMID 19936105, 2009). "One explanation is that S100B may be a prerequisite for neuroplastic changes that is required to improve depression, whereas BDNF may reflect the current state of recovery." (PMID 20046365, 2008). "Additionally, elevated S100β, NSE, and PLT are identified as key risk factors for depression." (PMID 40589656, 2025). "However, another study revealed that elevated serum S100B expression appeared to be an astrocyte-related molecular hallmark across different depression subtypes (psychotic, non-suicidal, and suicidal depression)." (PMID 39451987, 2024). "The administration of dexmedetomidine could improve postoperative cognitive dysfunction, emergence agitation, depression and anxiety, attenuate the plasma concentrations of S-100β and NSE and reduce the dosage of etomidate and remifentanil administered during surgery." (PMID 38273248, 2024). "The administration of dexmedetomidine could improve postoperative cognitive dysfunction, emergence agitation, depression and anxiety, attenuate the plasma concentrations of S-100β and NSE in older patients undergoing total intravenous anaesthesia with etomidate." (PMID 38273248, 2024). "Additionally, previous research has suggested that biomarkers like S100β, HMGB1, and NSE may not only reflect the progression of depression but also indicate an increased risk of neurodegenerative diseases associated with chronic depression." (PMID 39513898, 2024). "The administration of dexmedetomidine could improve postoperative cognitive dysfunction, emergence agitation, depression and anxiety, attenuate the plasma concentrations of S-100β and NSE and reduce the dosage of etomidate and remifentanil administered during the operation." (PMID 38273248, 2024). "In line with this hypothesis, an increase in plasma levels of markers of astrocytic activation, such as glial fibrillary acidic protein (GFAP) and S100β, are here shown to be significantly increased in patients with treatment-resistant depression when compared to healthy individuals." (PMID 38474387, 2024). "Finally, our newly diagnosed depressive patients suffered mainly from a “mild” form of depression, which could be of clinical significance, necessitating the further evaluation of S100B in more serious forms of depression in T2DM." (PMID 30581620, 2018).
depression (continued). "Therefore, the increased S100B expression in our model of depression may originate from the activated glial cells of the hippocampus and elevate the release of pro-inflammatory cytokines." (PMID 27931233, 2016). "Thus, fluctuations in serum levels of BDNF and S100B seem to be state markers for major depression." (PMID 26500502, 2015). "However, in neuropathological conditions, including those induced by environmental stressors, infection, ischemia, trauma, psychiatric conditions such as depression, and schizophrenia, the cellular and tissue distribution of S100B within the brain may change." (PMID 20827311, 2010). "Moreover, since serotonin has long been known to be related to depression, our findings may imply a role for S100B in depression." (PMID 20827311, 2010). "Moreover, it has been suggested that S100 proteins, such as S100B, may play a crucial role in the pathogenesis of depression and its treatment." (PMID 20585358, 2010). "Data support the hypothesis that elevated serum S100B is related to active secretion by astrocytes and/or oligodendrocytes in acute episodes of mood disorders, particularly major depressive disorder, and that this secretion might decline with successful antidepressive treatment." (PMID 20585358, 2010). "A depression signature (ρ = 0.19; P = .02) differentiated ROD from HC individuals with elevated IL-1β, IL-2, IL-4, S100B, and BDNF and GMV reductions in limbic regions." (PMID 41405910, 2025). "The expression of S100B and RAGE can be reduced by stress and depression, and these effects can be reversed or prevented by antidepressant treatment." (PMID 38783266, 2024). "While there is evidence supporting the potential role of ω-3 PUFAs in alleviating depression symptoms, studies specifically examining their effect on HMGB1, S100β, and NSE in individuals with depression are sparse." (PMID 39513898, 2024). "Among the 36 mRNAs associated with the ceRNA network, 3 mRNAs had been reported to be related to depression (DDIT4, S100B, Fbln2)." (PMID 35431783, 2022). "This study is one of the first to measure S100B and GFAP in the CSF of patients with unipolar depression." (PMID 34021122, 2021). "There is evidence for dysregulated S100B levels in MDD and a relation to antidepressant treatment: in an animal model of depression, brain S100B levels were shown to be increased, which could be decreased by conventional antidepressants." (PMID 34354565, 2021). "Brain derived neurotrophic factor (BDNF), S100B and neuron specific enolase (NSE) are among the most studied biomarkers in affective disorders, in particular major depressive disorder." (PMID 26500502, 2015). "In contrast to BDNF and S100B, serum NSE levels seem to be stable in depression suggesting mainly glial dysfunction." (PMID 26500502, 2015). "Selective serotonin re-uptake inhibitors are a mainstay of treatment for depression and infants exposed prenatally to SSRI's have lower levels of S100B." (PMID 20827311, 2010). "Therefore, we recommend that biomarkers such as S100β and NSE be included in routine screening for adolescent depression, alongside traditional psychological screening tools." (PMID 40589656, 2025). "However, there is no specific study focused on assessing the effect of ω-3 PUFAs on S100β, HMGB1, and NSE in depression." (PMID 39513898, 2024). "There have not been studies specifically dedicated to investigating the protective effects of ω-3 PUFAs on specific biomarkers such as S100β, HMGB1, and NSE in depression across animal models as well as pre-clinical and clinical research specifically related to depression." (PMID 39513898, 2024). "Most of the studies reported a lack of correlation of S100B levels with symptoms severity using different clinical scales: Hamilton Depression Rating Scale (HDRS), Clinical Global Impression (CGI), Mini-Mental State Examination (MMSE)." (PMID 37759935, 2023).